IL2RA (interleukin 2 receptor subunit alpha)
Diseases named in the same sentence as IL2RA in open-access papers (continued):
Sharing a sentence is not in itself a finding about the gene and the disease.
atopic dermatitis (3 papers, 2022 to 2025). "Genetic variations or the dysregulation of IL2RA have been linked to atopic dermatitis." (PMID 39859044, 2025). "Quantitative analysis revealed that the expression of NMB, IL2RA, IL1RL1, and PRKCQ was markedly elevated in individuals with atopic dermatitis relative to healthy controls (p < 0.05 or p < 0.01), indicating their possible involvement in disease development." (PMID 41346997, 2025).
dengue (3 papers, 2021 to 2023). "Moreover, IL2RA (CD25) showed a trend of upregulation in dengue disease." (PMID 35869167, 2022).
Hepatic fibrosis (3 papers, 2010 to 2023). The presence of excessive fibrous connective tissue in the liver. "On the other hand, the impact of other immunosuppressive agents including MMF, calcineurin inhibitors, sirolimus and IL-2RA on viral kinetics and progression of hepatic fibrosis after liver transplantation has not been well identified." (PMID 25013557, 2010).
IPEX syndrome (3 papers, 2019 to 2021). "IL-2RA mutations cause a phenotype similar to IPEX syndrome and CD25 deficiency can increase the vulnerability to viral infection." (PMID 33123017, 2020). "Individuals with recessively inherited IL2RA mutations develop immunodeficiency 31C syndrome, which is similar to IPEX syndrome (enteropathy, hypothyroidism and severe eczema) and can include neonatal-onset autoimmune diabetes." (PMID 30888520, 2019).
leprosy (3 papers, 2017 to 2024). Leprosy is a chronic infectious disease affecting primarily the skin and peripheral nervous system. "SNP rs2386841 of the IL2RA gene is associated with PB leprosy - Eleven markers at the IL2RA gene were tested in the start population, and rs2386841 and rs6602392 markers presented positive signal." (PMID 30540075, 2018). "As a result, our data points to IL2RA and TGFB1 associations with leprosy polarisation and help to construct the genetic architecture of this neglected phenotype." (PMID 30540075, 2018). "OBJECTIVES We conducted an association study for IL2RA and TGFB1 genes with clinical forms of leprosy based on two case-control samples." (PMID 30540075, 2018). "Applying the strategy proposed by Gaschignard and researchers, we conducted an association study of IL2RA and TGFB1 candidate genes in the “leprosy polarisation” phenotype, as this is a needy focus of inquiry in genetic epidemiology of leprosy." (PMID 30540075, 2018). "Furthermore, IL2RA is a positional candidate gene because it is located near the 10p13 chromosome region, presenting a linkage peak for PB leprosy." (PMID 30540075, 2018).
pulmonary tuberculosis (3 papers, 2008 to 2023). A bacterial infection that affects the lungs and is caused by Mycobacterium tuberculosis. "Our study identified unique gene signatures (IL-27, STAT1, IRF1, TLR4, IL-15, IL-2RA, IL-24, TGFβ, CD28, CD80, NFATC1, and PTGDR2) that discriminate active pulmonary TB from uninfected controls using unstimulated PBMCs." (PMID 37460564, 2023).
renal cell carcinoma (3 papers, 2018 to 2023). "A specific enrichment analysis of immune cells related to IGLL5 and IL2RA was also conducted in two types of renal cell cancer." (PMID 34888353, 2021).
severe combined immunodeficiency (3 papers, 2022 to 2024). Severe combined immunodeficiency (SCID) comprises a group of rare monogenic primary immunodeficiency disorders characterized by a lack of functional peripheral T lymphocytes resulting in early-onset severe respiratory infections and failure to thrive. "Such diseases include CD25 or IL-2RA deficiency, mutations within STAT5b, STAT1 or STAT3, Dedicator of Cytokinesis 8 (DOCK8) deficiency as well as infantile or eosinophilic enteropathies and severe combined immunodeficiency (SCID)." (PMID 35207219, 2022).
allergic asthma (2 papers, 2022 to 2025). A asthma with a basis in a pathological type I hypersensitivity reaction. "Several new loci are relevant to immunological pathways (e.g., 5p13.2 near IL7R, 10p15.2 near IL2RA, and 22q12.3 near IL2RB), including the allergic asthma locus IL4R (ORCRSwNP = 1.151 [1.104–1.199], p = 2.54e-11)." (PMID 41213931, 2025).
ankylosing spondylitis (2 papers, 2020 to 2025). An autoimmune chronic inflammatory disorder characterized by inflammation in the vertebral joints of the spine and sacroiliac joints. "Moreover, we found that IL2RA was regulated by several functional SNPs associated with ankylosing spondylitis." (PMID 32879140, 2020). "Collectively, these data suggest the potential drug repurposing opportunity of IL2RA on ankylosing spondylitis." (PMID 32879140, 2020). "For example, we predicted IL2RA to be a potential new drug target for ankylosing spondylitis." (PMID 32879140, 2020).
chronic graft versus host disease (2 papers, 2015 to 2026). Chronic graft versus host disease (GVHD) is a complication that can occur after a stem cell or bone marrow transplant in which the newly transplanted donor cells attack the transplant recipient's body. "Over the last 20 years we have progressed from discovering that IL-2 and IL-2RA are genetically associated with autoimmune diabetes and the functional state of Tregs to seeing dramatic clinical success with IL-2 in chronic GVHD." (PMID 25457307, 2015).
gastritis (2 papers, 2013 to 2024). Inflammation of the stomach. "Apart from these genes, targets like CCL2, IL6, JAK2, IL2RA and CXCR1 were also of vital importance in the Hot herbs’ targets network, which might infer us that another potential mechanism of Hot herbs against Cold ZEHNG gastritis was to regulate immune responses." (PMID 39367502, 2024).
glioblastoma (2 papers, 2024 to 2025). The most malignant astrocytic tumor (WHO grade IV). "In glioblastoma, OPALIN, LTF, IL2RA, and SLC17A7 were implicated in Temozolomide resistance through pathways related to epithelial differentiation and angiogenesis." (PMID 41020875, 2025). "In glioblastoma treated with Temozolomide, the models prioritized OPALIN, LTF, IL2RA, and SLC17A7 as candidate resistance related genes." (PMID 41020875, 2025).
graft versus host disease (2 papers, 2012 to 2022). An immune system disorder that occurs after allogeneic hematopoietic stem cell transplant and is a reaction of donor immune cells against host tissues. "Prodigiosin also suppressed IL-2Rα expression in the IL-2/IL-2R signalling to block T-cell activation, inhibiting graft versus host disease (GvHD) and delayed the progression of autoimmune diabetes without toxicity in mice." (PMID 36577970, 2022).
Hearing impairment (2 papers, 2023 to 2025). A decreased magnitude of the sensory perception of sound. "Cisplatin-induced hearing loss was associated with increased levels of three circulating cytokines: M-CSF (OR: 1.04, 95% CI: 1.01–1.08, P = 0.010, FDR = 0.41); IL-2RA (OR: 1.03, 95% CI: 1.00–1.05, P = 0.044, FDR = 0.447); and MIP-1β (OR: 1.02, 95% CI: 1.00–1.04, P = 0.041, FDR = 0.447)." (PMID 37919361, 2023).
liver cirrhosis (2 papers, 2010 to 2025). "In more detail, levels of the pro-inflammatory mediators CRP, tPA, IL-6, IL-8, HGF, M-CSF, IL-2Ra, IP-10, and MIP-1a were significantly increased in patients with decompensated liver cirrhosis compared with healthy controls." (PMID 41028194, 2025).
metastatic disease (2 papers, 2011 to 2020). "Specifically, CXCR6, CCR2, CCR4, IL2Ra were both deleted and had lower gene expression in the primary versus metastatic tumors." (PMID 22194851, 2011).
neutropenia (2 papers, 2024 to 2026). A decrease in the number of neutrophils found in the blood. "To determine the extent of CAR-T–associated neutropenia, we compared neutrophil levels of IL-2Ra KO mice treated with WT CAR-T alone, or lymphodepletion alone, or in combination." (PMID 41165751, 2026).
pancreatic cancer (2 papers, 2022 to 2023). "Pancreatic cancer of KEGG pathway and epithelial mesenchymal transition of hallmarks also might be activated by IL2RA." (PMID 36281157, 2022).
pancreatic ductal adenocarcinoma (2 papers, 2022 to 2024). An infiltrating adenocarcinoma that arises from the epithelial cells of the pancreas. "High IL2RA expression, observed in the alpha chain of the interleukin 2 receptor complex on mature T cells, has been shown to correlate with unfavorable survival outcomes in pancreatic ductal adenocarcinoma patients." (PMID 38254897, 2024).
renal carcinoma (2 papers, 2009 to 2023). A carcinoma arising from the epithelium of the renal parenchyma or the renal pelvis. "Immunohistochemistry showed the infiltrating distribution of Treg cell marker proteins FOXP3 and IL2RA in renal carcinoma tissue from the Human Protein Atlas database." (PMID 36846720, 2023).
thyroid cancer (2 papers, 2021 to 2023). "Among them, TSHR and RNASET2 were highly expressed in malignant tumors, especially TSHR in thyroid cancer, while BACH2, CTLA4, PTPN22, IL2RA, and other immune-related genes are expressed significantly lower in thyroid cancer." (PMID 34993154, 2021). "Our research group used bioinformatics to analyze the Oncomine database and found that HT-related genes (TSHR, BACH2, RNASET2, CTLA4, PTPN22, IL2RA) were expressed in different types of thyroid cancer." (PMID 34993154, 2021). "Also, the infiltration of interleukin 2 receptor subunit alpha (IL2RA)+ V-set and immunoglobulin domain-containing protein 4 (VSIG4)+ ATC-associated macrophages (ATAMs) showed a strong correlation with BRAF and RAS signalling and was associated with a favourable prognosis in thyroid cancer patients." (PMID 38129369, 2023).
abscess (1 paper, 2025). An inflammatory process characterized by the accumulation of pus within a newly formed tissue cavity which is the result of a bacterial, fungal, or parasitic infection or the presence of a foreign body. "We hypothesize that the IL2RA+ M1-like clusters make up the macrophage collar that surrounds the abscess, since they express transcripts corresponding to IDO1, anti-oxidative defenses, and MMPs." (PMID 39882906, 2025).
acute coronary syndrome (1 paper, 2024). Signs and symptoms related to acute ischemia of the myocardium secondary to coronary artery disease. "One such CK-CKR pair is the interaction interface between IL2 and IL2RA, which may be targeted for better treatment of Acute Coronary Syndrome." (PMID 38789577, 2024).
acute lymphoblastic leukaemia (1 paper, 2020). "In addition, the proto–oncogene MYC and interleukin 2 receptor subunit Alpha (IL2RA) are implicated in the prognosis of acute lymphoblastic leukaemia." (PMID 32887470, 2020).
adenoma (1 paper, 2024). A neoplasm arising from the epithelium. "Furthermore, single-cell RNA-sequencing data showed that the expression of IL-2RA (CD25) and FOXP3, the key markers of Treg cells, was increased from adenoma to carcinoma in the tissue-derived CD4+ T cells, which is consistent with the changes in peripheral Treg cells." (PMID 38343544, 2024).
agranulocytosis (1 paper, 2025). "Clozapine‐induced IL2RA effects in T‐cells may lead to agranulocytosis." (PMID 39776289, 2025). "The PPI and KEGG enrichment pathway analyses demonstrated that clozapine induces agranulocytosis by modulating the hematopoietic cell lineage and JAK–STAT signaling pathways via interleukin‐3 (IL3), IL6, IL2 receptor subunit alpha (IL2RA), and granulocyte colony‐stimulating factor." (PMID 39776289, 2025).
anorexia nervosa (1 paper, 2024). A disorder most often seen in adolescent females characterized by a refusal to maintain a minimally normal body weight, an intense fear of gaining weight, a disturbance in body image, and, in postmenarcheal females, the development of amenorrhea. "For anorexia nervosa, per one-unit increase in genetically predicted log odds of T1D as measured by the IL2RA cis instrument, there was a 12% decrease in odds using the secondary weighted median method only (OR = 0.88; 95% CI = 0.81–0.96; P = 0.003; adjusted P = 0.012)." (PMID 39263363, 2024).
anterior uveitis (1 paper, 2013). Inflammation of the iris and anterior chamber of the eye. "Our results indicate that analyzed IL2/IL21, IL2RA and IL2RB polymorphisms do not seem to play a significant role on the non-anterior uveitis genetic predisposition although further studies are needed in order to clear up the influence of these loci on the non-anterior uveitis susceptibility." (PMID 23676143, 2013).
conjunctivitis (1 paper, 2024). Inflammation of the conjunctiva of the eye. "The expression of IL2RA is closely associated with the severity of inflammation in the conjunctivitis mouse model." (PMID 39295864, 2024).
cutaneous leishmaniasis (1 paper, 2018). Leishmaniasis affecting the skin. "Polymorphisms at the IL2RA gene are associated with lesion development in cutaneous leishmaniasis in Brazilian populations." (PMID 30540075, 2018).
dental caries (1 paper, 2024). The decay of a tooth, in which it becomes softened, discolored, and/or porous. "There is evidence that some salivary compounds studied in this review could play an important diagnostic role for dental caries, such as salivary mucins, glycoproteins (sCD14), interleukins (IL-2RA, 4,-13), urease, carbonic anhydrase VI, and urea." (PMID 38785526, 2024).
diabetic retinopathy (1 paper, 2020). "In addition, elevated levels of soluble IL-2R alpha (sIL-2R; alternative: IL-2RA, CD25) have been reported to be an important factor in the development of diabetic retinopathy in non-insulin-dependent diabetes patients and coronary artery calcification in T1D patients." (PMID 33193091, 2020).
gastric polyps (1 paper, 2024). "The IVW method revealed a potential link between genetically determined higher interleukin-2 receptor subunit alpha (IL-2ra) levels (one-SD increase) and a suggestive 11% reduction in the likelihood of developing gastric polyps (OR: 0.892, 95%CI: 0.828–0.961, p = 0.003)." (PMID 39439893, 2024).
gout (1 paper, 2022). A condition characterized by painful swelling of the joints, which is caused by deposition of urate crystals. "We identified 256 eccDNA-associated genes solely represented in gout patients compared to healthy controls, from which we identified a couple of genes involved in inflammatory response, including TLR6, IL2RA, PTGS1, MAPK13, CHRNA4, GCH1, and IL5." (PMID 35464862, 2022). "IL2RA is the receptor of IL-2, and IL-2 is the inflammatory markers of gout." (PMID 35464862, 2022).
head and neck cancer (1 paper, 2022). A primary or metastatic malignant neoplasm affecting the head and neck. "However, they appear to be associated with improved OS in head and neck cancers, which is consistent with our finding that high expression levels of IL2RA were associated with favorable survival in HNSCC patients." (PMID 36097539, 2022).
infarction (1 paper, 2020). A localised pathological necrosis of tissue resulting from obstruction of the blood supply usually by a thrombus, an embolus, or vascular torsion. "For both infarction groups, we found significantly higher levels of interleukin-2 receptor subunit alpha (IL2-RA) and growth/differentiation factor-15 (GDF-15)." (PMID 33396480, 2020).
lymph node metastases (1 paper, 2025). "To investigate the potential role of CD4+ Tregs in lymph node metastases, we identified the upregulated genes in CD4+ Tregs from metastatic lymph nodes, including IFI27, IL2RA and IL2RB." (PMID 39741182, 2025).
Merkel cell skin cancer (1 paper, 2024). A carcinoma arising from MERKEL CELLS located in the basal layer of the epidermis and occurring most commonly as a primary neuroendocrine carcinoma of the skin. "Also, ipilimumab, a cytotoxic T-lymphocyte protein 4 inhibitor, targets CTLA4, and aldesleukin, an interleukin-2 receptor agonist, targets IL2RA; current clinical trials are testing therapies based on these drugs for Merkel cell skin cancer and other skin cancers." (PMID 38182794, 2024).
neuromyelitis optica (1 paper, 2021). A rare inflammatory disease of the central nervous system characterized mainly by attacks of uni- or bilateral optic neuritis (ON) and acute myelitis. "The allele (rs2104286 G) of IL2RA was also found to have a higher frequency in patients with neuromyelitis optica than in healthy controls, suggesting that this IL2RA allele is associated with an increased risk of this neurological disorder." (PMID 34485395, 2021).
osteonecrosis (1 paper, 2024). A none disease characterized by death of bone tissue due to a lack of blood supply. "The identification of bFGF, IL-2, and IL-2RA as causally linked to osteonecrosis suggests promising avenues for potential therapeutic interventions." (PMID 38745949, 2024). "In our current investigation, our findings strongly indicate a causal relationship between elevated levels of bFGF/IL-2RA and an increased risk of osteonecrosis." (PMID 38745949, 2024). "It conclusively establishes a causal association between osteonecrosis and bFGF, IL-2, and IL-2RA." (PMID 38745949, 2024). "Notably, the study unequivocally establishes a causal association between bFGF, IL-2, and IL-2RA with osteonecrosis." (PMID 38745949, 2024). "Furthermore, heightened IL-2RA levels were associated with an elevated risk of osteonecrosis (OR=1.386, 95% CI=1.04-1.85, p=0.026), while increased IL-2 levels were linked to a decreased risk (OR=0.688, 95% CI=0.50-0.94, p=0.021, per 1 standard deviation (SD) increase)." (PMID 38745949, 2024). "The study suggests bFGF, IL-2, and IL-2RA as potential therapeutic targets for osteonecrosis treatment." (PMID 38745949, 2024). "According to our present MR analysis, bFGF in conjunction with IL-2RA may contribute to the development of osteonecrosis, while IL-2 exhibits an opposing effect." (PMID 38745949, 2024). "With the exception of bFGF, IL-2RA, and IL-2, other cytokines such as VEGF, GRO-α, Trail, MIG, IL-7, and IL-17 did not demonstrate any association with osteonecrosis risk in the IVW primary MR analysis or secondary analyses." (PMID 38745949, 2024).
pancolitis (1 paper, 2021). Ulcerative colitis that involves the entire colon. "Here, we identify a de novo duplication of the 10p15.1 chromosomal region, including the IL2RA locus, in a 2-year-old girl with treatment-resistant pancolitis that was brought into remission by colectomy." (PMID 34226674, 2021).
papillary renal cell carcinoma (1 paper, 2023). A rare subtype of renal cell carcinoma, arising from the renal tubular epithelium and showing a papillary growth pattern, which typically manifests with hematuria, flank pain, palpable abdominal mass or nonspecific symptoms, such as fatigue, weight loss or fever. "Although TME existed heterogeneity, one study identified the core immune-related genes (IGLL5 and IL2RA) in ccRCC and papillary renal cell carcinoma." (PMID 37108666, 2023).
polyarticular JIA (1 paper, 2020). "We identified enhancer function within the first intron of IL2RA, and, furthermore, demonstrated that genetic variants that we had previously identified on WGS of patients with polyarticular JIA attenuate that function." (PMID 32730263, 2020). "For these experiments, we first tested 2 variants within the IL2RA intronic enhancer, rs117119468 (C->T), and rs12722502 (C->T), that we had identified on whole genome sequencing (WGS) of a small number of children with polyarticular JIA." (PMID 32730263, 2020).
primary progressive MS (1 paper, 2020). "IL2RA is a drug-target gene of ocrelizumad, a recently FDA approved drug for treatment of both relapsing-remitting and primary progressive MS, and was present within our top gene module of IMSGC and the top gene module of our dual evaluation." (PMID 32241259, 2020).
rectal cancer (1 paper, 2014). A primary or metastatic malignant neoplasm that affects the rectum. "Seven genes (IL2RA, IL8RA, IL8RB, IRF2, RAF1, RUNX3, and SEPX1) were significantly associated with rectal cancer (PARTP<0.05)." (PMID 25541970, 2014).